KPNA2 (karyopherin subunit alpha 2)
Diseases named in the same sentence as KPNA2 in open-access papers (continued):
Sharing a sentence is not in itself a finding about the gene and the disease.
tumor (continued). "Importantly, KPNA2 is upregulated in several tumor cell lines and its levels correlates with the oncogenic potential by promoting proliferation, cell growth, migration, invasion, and tumor formation." (PMID 37792911, 2023). "Taken together, our results revealed clusters of malignant cells that resembled normal lung cell subclusters and a cluster (cluster 4) was with stem-like proliferating features in malignant basal cells, and its maker KPNA2 might promote tumor proliferation in LUSC." (PMID 35027529, 2022). "Given that KPNA2 binds to oncoproteins and tumor suppressor proteins indistinctively, it might depend on oncogenic or tumor suppressive signaling and specific space-temporal contexts to distinctively regulate the transport of oncoproteins and tumor suppressor proteins." (PMID 34616632, 2021). "In terms of functional data, KPNA2 overexpression induced cell migration, cell viability, and cell proliferation of cancer cells, which indicates that abnormal expression of nuclear transporters in cancer cells interferes with cellular homeostasis and thereby contributes to tumor pathogenesis." (PMID 33728352, 2021). "Diverse studies on animal tumour models could demonstrate that the proliferation rate of cancer cells increases significantly upon overexpression of KPNA2; in turn, the proliferation decreases upon KPNA2 antagonism." (PMID 30323892, 2018). "Furthermore, xenograft tumor mouse model experiments showed that KPNA2 knockdown could inhibit tumorigenesis in vivo." (PMID 28422734, 2017). "Hence, KPNA2-bind cargo protein may synergize with KPNA2 in the occurrence and development of tumor." (PMID 27611951, 2016). "KPNA2 may be an important promoter of ribosomal RNA and protein synthesis in tumor cells." (PMID 24098495, 2013). "KPNA2 and TKT were broadly and highly expressed within tumor regions, suggesting their potential involvement in tumor proliferation or metabolic activity." (PMID 41602397, 2026). "To further investigate the expression and functional role of KPNA2 in HCC, we initially examined KPNA2 mRNA expression in 16 pairs of tumor and adjacent peritumor tissues from HCC patients using qRT-PCR." (PMID 40665355, 2025). "We found the increased expression of PFKP, TPX2, UBE2S, ST6GALNAC4, ADAM15, G6PD, and KPNA2, but decreased expression of GOT2 in tumor samples compared to normal samples." (PMID 40307857, 2025). "Current immunohistochemical (IHC) and molecular analyses, including RUNX2, KPNA2, and SATB2 as biomarkers, support the osteogenic origin of the tumor and assist in differentiating OS from morphologically similar neoplasms." (PMID 40862758, 2025). "We validated that KPNA2 is involved in telomere maintenance in HCC cells and plays a significant role in regulating tumor proliferation and migration." (PMID 40665355, 2025). "By interaction with KPNA2, the NLS-FF-T transformed into a nanofibrous-based ATP trapper on the surface of tumor nuclei, which prevented the production of intracellular energy." (PMID 38425424, 2024). "Further analysis of the model genes within TCM across pan‐cancer settings revealed that TOMM40, NNT5DC2, NNME, KPNA2, FFOXM1 and AP2S1 were predominantly overexpressed in tumour tissues, while TYRP were highly expressed in normal tissues." (PMID 39054572, 2024). "Functional assays demonstrated that two miRNAs acted as tumor-suppressive miRNAs in BC cells by targeting cell-cycle-related genes (e.g., TRIP13, CCNB1, RAD51, PSPH, CENPN, KPNA2, and MXRA5)." (PMID 39728605, 2024). "As immune cells in the tumor microenvironment (TME) impact patient prognosis, exploring the correlation between KPNA2 expression and immune infiltration is a valuable area of research." (PMID 39060340, 2024).
tumor (continued). "Upon interaction with KPNA2, the NLS-FF-T transformed into nanofibrous-based ATP traps on the surface of tumor nuclei, hindering intracellular energy production." (PMID 38425424, 2024). "Various studies have highlighted that nuclear transport receptors including XPO1, KPNA2, and KPNA4, exhibit hyperactivity in cancer and facilitate the export of vital tumor suppressors to the cytoplasm or the import of oncogenes to the nucleus." (PMID 38820302, 2024). "KPNA2, BZW2 and KIF15 were involved in protein synthesis and transport and were suggested to be related to tumor progression." (PMID 37202800, 2023). "For further characterization of PHCs, the expression of the following HCC-specific tumor markers was investigated: GPC3, SPINK1, SPP1 and KPNA2." (PMID 36077764, 2022). "Some studies have shown that KPNA2 and STAT3 colocalize in the nucleoplasm of tumour cells, and IP results in fibroblast-like synoviocytes suggest that KPNA2 binds STAT3." (PMID 36578083, 2022). "Karyopherin subunit alpha 2 (KPNA2), a member of the nuclear transport protein family, was recently shown to be induced by hypoxia in various types of tumours, so we aimed to investigate the role and mechanism of KPNA2 in angiogenesis under hypoxia." (PMID 36578083, 2022). "On the other hand, it was reported that RNA-interference-mediated KPNA2 silencing completely inhibited the proliferation and migration of MCF7 tumor cells." (PMID 35991835, 2022). "Freshly isolated cells were additionally characterized for specific mRNA expression of tumor (GPC3, SPINK1, SPP1, KPNA2) and fibroblast (COL1A2, TWIST2, FGF7) marker genes using RT–qPCR." (PMID 36077764, 2022). "Through conducting functional and mechanistic studies, we identified that KPNA2, a central importin in nuclear import, maintained PD-L1 expression by mediating nuclear translocation of STAT3 and ultimately led to tumor immune evasion." (PMID 33728352, 2021). "Furthermore, PRDM1 overexpression could counteract the pro-tumor effects of KPNA2." (PMID 33731128, 2021). "A review of the literature found that six of the 12 upregulated genes (KPNA2, CDK1, TARBP1, PRC1, FEN1, and MCM6) were overexpressed in HCC tissue compared to levels in non-tumor tissue based on immunohistochemical staining." (PMID 32213663, 2020). "Since KPNA2 is involved in nucleocytoplasmic transport of proteins, we investigated the effects of miR-139 overexpression and KPNA2 depletion on the nucleus transportation of c-myc and POU5F1, which have been reported to promote tumor growth in nucleus." (PMID 31046781, 2019). "Among all the hub genes, KPNA2 and EZH2, which are tumor-promoting genes, have been extensively studied and were found to be the most effective predictors of survival time." (PMID 31695969, 2019). "The genes, ZWINT, E2F1, HMGB2, KPNA2, and CKS2, were expressed at low or moderate levels in non-tumor tissues." (PMID 31695969, 2019). "While increased expression of KPNA2 promotes proliferation and survival of GBM tumour cells, silencing of KPNA2 conferred a less malignant behaviour." (PMID 30323892, 2018). "The muscle invasive tumour, however, showed a basal subtype (higher expression of CDH3, CD44, KRT5 and KRT6A) and likewise high aggressiveness (higher expression of KPNA2, BIRC5, CDC25B, COL4A1, and MSN)." (PMID 28916750, 2017). "Up-regulated KPNA2 and OCT4 expression were positively correlated with primary tumor stage and pathological types." (PMID 27611951, 2016). "Further dot plot analysis revealed that TKT and KPNA2 were relatively highly expressed in epithelial and myeloid cells, with TKT showing notably higher expression in tumor epithelial cells compared to normal epithelial cells, suggesting its potential involvement in tumorigenesis or progression." (PMID 41602397, 2026). "Notably, G6PD was predominantly expressed in early and mid-stages, while KPNA2, PFKP, and TPX2 were upregulated in advanced tumor states." (PMID 40307857, 2025).
tumor (continued). "Notably, only KPNA2 had been found in our previous study to be the crucial transporter of transcription factor CREB3L1 into the nucleus and remodel the tumor microenvironment to promote tumor growth and metastasis in ATC." (PMID 37501099, 2023). "In addition, IHC methods were employed to detect the expression of KPNA2 and important markers of EMT in tumor tissues of mice, including E-cadherin, N-cadherin, and Vimentin." (PMID 35136045, 2022). "Our findings also revealed significant correlations between KPNA2, LPCAT1, KIF2C, and SPP2 expression and three clinical traits, including ECOG (p < 0.01), vascular tumour cell type (p < 0.05), and tumour status (p < 0.05)." (PMID 35915607, 2022). "Increased expression of KPNA2 protein was observed in tumor tissues by immunofluorescence staining in comparison to normal lung tissues." (PMID 35027529, 2022). "CCK8, colony formation, wound healing, and Transwell assays were used to assess cell viability, proliferation, and migration in vitro, and in vivo experiments were performed to explore the effects of KPNA2 and interferon regulatory factor-2 (IRF2) on tumor growth." (PMID 36199790, 2022). "The role of KPNA2 in HCC immunoregulation was highlighted, providing information of immune cell constitutions within HCC microenvironment and for prediction of HCC immune response, and constituting a potential resource in anti-tumor immunotherapy." (PMID 34616632, 2021). "In this study, we verified that aberrantly increased KPNA2 contributed to PDAC progress by maintaining tumor immune evasion rather than impacting the malignant properties of tumor cells." (PMID 33728352, 2021). "In our preliminary bioinformatics analysis on public datasets of HCC, KPNA2 was highlighted to be a unique independent predictor for poor OS of HCC among the differentially expressed genes, and the other independent indicator was tumor stage." (PMID 34616632, 2021). "KPNA2 immunoreactivity was independent of conventional factors, such as sex, tumor multiplicity, and tumor location." (PMID 25956057, 2015). "Furthermore, we have observed that the interaction between KPNA2 and Kinesin Family Member C1 (KIFC1) facilitates the transition of BCa cells into the G2/M phase, thereby promoting tumor advancement via activation of the Phosphoinositide 3-kinase (PI3K)- Protein Kinase B (AKT) pathway." (PMID 39956902, 2025). "Regarding the macrophage differentiation in the tumor microenvironment, conditioned media from Kpna2-overexpressing LFs showed little or no differential effect in inducing polarization of Raw264.7 murine macrophages compared with conditioned media from control LFs." (PMID 35884546, 2022). "Since silencing KPNA2 significantly impeded the in vivo tumor growth but failed to impair the vitality and migration ability of PDAC cells in vitro, we guessed whether upregulated KPNA2 leads to tumor progression via contributing to tumor immune evasion." (PMID 33728352, 2021). "Overexpression of KPNA2 was previously reported in LUAD tissues and negatively regulated by a novel transcription factor interferon regulatory factor-1 (IRF1).47,48 Our study revealed that KPNA2 may be a proliferating marker and promote tumor progression in LUSC." (PMID 35027529, 2022). "Moreover, high nuclear KPNA2 immunoreactivity was identified as a novel predictor of bladder recurrence and poor DFS and OS of UTUC patients after RNU, and its predictive ability was independent of the conventional predictive factors such as sex, tumor location, tumor size, and tumor multiplicity." (PMID 25956057, 2015). "KPNA2 promotes the phosphorylation of AKT and GSK-3β in tumour cells without altering the expression of total AKT or GSK3β." (PMID 36578083, 2022). "The expression of KPNA2 and CBX8 was correlated with the pathological grade, clinical stage, metastasis, and recurrence of the tumor (p < 0.05), but not correlated with age, gender, smoking history, and gross hematuria (p > 0.05)." (PMID 33731128, 2021).
tumor (continued). "Although KPNA2 knockdown failed to impair the vitality and migration ability of PDAC cells in vitro, the in vivo tumor growth was significantly impeded and the expression of immune checkpoint ligand PD-L1 was reduced by silencing KPNA2." (PMID 33728352, 2021). "Moreover, the expression levels of KPNA2, PFKFB4, and SPP1 in HCC tumour tissues were significantly higher than those in adjacent normal tissues." (PMID 36873244, 2023).
cancer (90 papers, 2013 to 2025). A tumor composed of atypical neoplastic, often pleomorphic cells that invade other tissues. "In the literature, the overexpression of KPNA2 exists in many types of cancers, including HCC, associated with poor prognosis." (PMID 40665355, 2025). "Since MFS is also a predictor of survival in various cancers, the association of KPNA2 expression and MFS was studied using the GSE7390 dataset with two different KPNA2 probes." (PMID 40002266, 2025). "Recent studies have shown that KPNA2 is upregulated in a variety of malignant tumours, and the high expression of KPNA2 is closely associated with poor prognosis after surgery and can be used as an independent prognostic indicator in some malignant tumours." (PMID 37423952, 2023). "Kpna2 overexpression has been linked to various human cancers, including, breast, ovarian endodermal sinus and ovarian primitive germ cell tumours." (PMID 37398910, 2023). "KPNA2, a member of the nuclear transporter family, had recently been found to be involved in the nuclear entry of cancer stemness-associated transcription factor c-MYC." (PMID 37501099, 2023). "KPNA2 protein, which is involved in the nucleocytoplasmic transport, is overexpressed in various cancers and associated with poor prognosis." (PMID 37048099, 2023). "In sinonasal papilloma, KPNA2 levels were associated with cancer cell differentiation and proliferation and showed potential cancer recurrence biomarkers." (PMID 35860570, 2022). "Taken together, our findings from analyses of KPNA2 expression levels, mutational signature, impact on prognostic endpoints and co-expression patterns evidence that KPNA2 is implicated in cancer progression and prognosis." (PMID 35948941, 2022). "Aberrant amplification of KPNA2 expression in cancer has been implicated in the pathogenic mislocalization of substrate proteins, resulting in tumorigenesis and conferring an aggressive sub-phenotype." (PMID 35948941, 2022). "Recently, several studies have linked KPNA2 to various cancers, such as lung, breast, colon, and pulmonary cancer." (PMID 36199790, 2022). "Emerging evidence revealed that karyopherin alpha 2 (KPNA2) was strongly associated with the tumorigenesis and development of numerous human cancers." (PMID 36199790, 2022). "Our findings are in agreement with a previous report indicating that KPNA2 overexpression can serve as a prognostic marker across multiple cancer types and is associated with malignant transformation and poor patient survival." (PMID 35948941, 2022). "KPNA2 mutations, especially missense substitution, were widely identified in six cancers and interact with different genes in different cancer types." (PMID 33821218, 2021). "The mutation status of KPNA2 in the six major cancers was evaluated by online data analysis tool Catalog of Somatic Mutations in Cancer (COSMIC) and cBioPortal." (PMID 33821218, 2021). "KPNA2 belongs to the importin α family, which plays important roles in nucleocytoplasmic transport; and KPNA2 has been reported to promote carcinogenesis through translocation of cancer-associated cargo proteins, including tumor suppressor and oncogenes." (PMID 31046781, 2019). "Karyopherin α2 (KPNA2), which is implicated in nucleocytoplasmic transport of various proteins, has been demonstrated as showing aberrantly high expression in cancers of several types." (PMID 31179341, 2019). "KPNA2 is shown to participate in the translocation of cancer-associated cargo proteins, such as Chk2, BRCA1, NBS1 and many others." (PMID 27974678, 2017). "The overall pooled results from these cancer types indicated that elevated KPNA2 expression was associated with patients' poor OS, TTR, RFS and PFS." (PMID 27974678, 2017). "Several studies revealed that high KPNA2 expression is associated with cancer progression and poor prognosis, suggesting KPNA2 as a potential prognostic marker." (PMID 28178675, 2017).